FAM90A9 (family with sequence similarity 90 member A9)
Synonyms: FAM90A9P
Tractability: No criterion of Open Targets' tractability assessment is met for any kind of drug.
Gene: Protein-coding gene on chromosome 8 (7,761,330 to 7,764,340, forward strand). Ensembl gene ENSG00000285607.
Subcellular location (Human Protein Atlas): Nucleoplasm; Nucleoli
Homologues: Orthologues: mouse Fam90a1b (29% identical), mouse Fam90a1a (27% identical), rat Fam90a1l1 (26% identical). Paralogues in human: FAM90A16 (99% identical), FAM90A17 (99% identical), FAM90A18 (99% identical), FAM90A19 (99% identical), FAM90A8 (99% identical), FAM90A15 (98% identical), FAM90A13 (98% identical), FAM90A14 (98% identical), FAM90A23 (98% identical), FAM90A3 (98% identical), FAM90A5 (98% identical), FAM90A10 (98% identical), and 9 more.